IL6 (interleukin 6)
Diseases named in the same sentence as IL6 in open-access papers (continued):
Sharing a sentence is not in itself a finding about the gene and the disease.
neutropenia (continued). "In addition to the elevated levels of TNFα and IL-6, we also observed that IL-10 was enhanced by neutropenia during LPS-induced inflammation at both time points investigated." (PMID 40534875, 2025). "Laboratory results, including higher ferritin level, longer duration of neutropenia, an increase in inflammatory cytokines such as plasma and salivary interleukin-6, and presence of specific bacterial and fungal species in oral microbiota, demonstrated increased risk of OM in six studies." (PMID 40867286, 2025). "Tocilizumab is thought to help suppress the hyperinflammatory response and reduce mortality, thus recommended for patients with human coronavirus if serum IL‐6 content is over 20 pg/mL despite prolonging neutropenia, even after the resolution of acute symptoms." (PMID 39980892, 2025). "IL6 independently regulates granulopoiesis and IL‐6 receptor blockers induce neutropenia." (PMID 39776289, 2025). "CRS treatment with interleukin-6 (IL-6) and/or steroids may alter or mask the clinical presentation of infection, especially in the setting of concomitant neutropenia." (PMID 39084261, 2024). "Furthermore, lymphocytopenia and neutropenia due to bone marrow invasion additionally hamstring immunity, while cytokines excreted by malignant cells (e.g., IL-6, IL-10, TGF-b) impair T-cell response to infection." (PMID 39065149, 2024). "Furthermore, the side effects of anti-IL-6 and anti-IL-6R antibody therapy include neutropenia, abnormal liver function, and respiratory infections, including TB." (PMID 37854602, 2023). "In Barth syndrome, while patients experience recurrent bacterial infections due to neutropenia, they also have persistently elevated plasma levels of the inflammatory cytokine interleukin 6 (IL-6), consistent with chronic inflammation, which are thought to contribute to muscle-wasting." (PMID 36056365, 2022). "Thus, the administration of IL-6 inhibitors would result in margination of neutrophils and, therefore, neutropenia." (PMID 36091800, 2022). "The occurrence of neutropenia as an adverse effect of the IL6 inhibitor, tocilizumab, could also demonstrate the relationship between IL6 and neutrophil survival." (PMID 33958640, 2021). "JAK inhibitors including tofacitinib and baricitinib, which target signaling down-stream of cytokine receptors including IL-6, interferon-α and -γ, and GM-CSF receptors, are clinically effective in treating RA although many patients report transient neutropenia and increased infections." (PMID 33469455, 2020). "Furthermore, neutropenia with TCZ is undoubtedly due to the inhibition of the biologic influence of IL-6 on the recruitment of neutrophils into peripheral blood." (PMID 32344563, 2020). "Future therapies could potentially target the marked elevations in IL-6 and IL-8, limiting neutrophil recruitment and subsequent lung injury in patients predictably recovering from neutropenia, such as those undergoing cytotoxic chemotherapy." (PMID 27431667, 2016). "Although neutropenia was more likely in patients with a hematologic diagnosis, previous chemotherapy, and allogeneic hematopoietic stem cell transplantation (HSCT), none of these factors other than neutropenia itself was independently associated with higher IL-6 levels." (PMID 41155261, 2025). "Importantly, while neutropenia was associated with highly elevated IL-6, this did not translate into significant differences in IL-6 concentrations between survivors and non-survivors within the neutropenic subgroup." (PMID 41155261, 2025). "The gender, age, neutropenia, specimen distribution, CMT, and mNGS positivity; CRP, PCT, IL-6, and IL-10 levels; and the agreement rate of mNGS with clinic were all comparable between the two groups." (PMID 35391735, 2022). "Among these cytokines, IL-6 is a particularly important regulator of myeloid differentiation and HSPC proliferation and in mediating rapid myeloid cell recovery during neutropenia." (PMID 32373117, 2020).
neutropenia (continued). "In this setting, transitory Grade 1–2 neutropenia related to biotherapy is relatively common with several biotherapies (e.g., TNF-alpha inhibitors, IL6 inhibitors, and anti-CD52 agents)." (PMID 31480527, 2019). "An approximate 10% prevalence of such neutropenia has been reported with several of these biotherapies (e.g., TNF-alpha inhibitors, IL6 inhibitors, and anti-CD52 agents)." (PMID 31480527, 2019). "The concentrations of tumor necrosis factor-α, interleukin (IL)-1β, IL-6 and myeloperoxidase in BAL fluid were significantly inhibited by imatinib or nilotinib in mice of ALI during neutropenia recovery." (PMID 23787115, 2013). "We found that the concentrations of TNF-α, IL-6, IL-1ß, and MPO were dramatically increased in BAL fluid after LPS administration during neutropenia recovery." (PMID 23787115, 2013). "• Administration of imatinib or nilotinib before instillation of LPS during neutropenia recovery significantly downregulated several inflammatory and chemotactic cytokines, such as TNF-α, IL-6 and IL-1ß." (PMID 23787115, 2013). "Despite these pronounced elevations, IL-6 alone provided only limited prognostic information for mortality, and neutropenia, while strongly influencing IL-6 levels, did not independently affect outcomes." (PMID 41155261, 2025). "In toll-like receptor (TLR) stimulation, IL-6 has been shown as a signaling hub and a particularly important regulator of myeloid differentiation and HSPC proliferation in a paracrine manner, which mediates rapid myeloid cell recovery during neutropenia." (PMID 34353116, 2022). "Subjects with neutropenia had significantly higher plasma IL-6 and IL-8 levels than non-neutropenic subjects." (PMID 27431667, 2016). "IL-6 and IL-8 did not prove useful to prevent bloodstream infection before chemotherapy, on the first day of neutropenia nor subsequent days." (PMID 26543528, 2015). "IL-6 is less studied and it is not known how IL-6 injections affect HSCs, but blocking IL-6 signaling inhibits expression of inflammatory genes in HSCs in response to LPS during neutropenia or in response to murine hepatitis virus 1 (MHV-1) in mice or SARS-CoV2 in humans." (PMID 39720722, 2024). "Others reported that IL-6 did not directly act as a neutrophil chemoattractant or induce apoptosis, although its therapeutic inhibition by tocilizumab induces neutropenia." (PMID 29497762, 2018). "While the single treatment with Ruxolitinib did reduce the APP response after treatment with IL-6, more sustained inhibition may still be of importance, but an increase in dose is not desirable due to harmful side-effects such as neutropenia." (PMID 29062282, 2017). "Interestingly, neutropenic patients had particularly high IL-6 plasma concentrations (median IL-6 plasma concentration 7866 pg/mL (IQR 333-62,835 pg/mL, n = 31) and 130 (IQR 35–684 pg/mL, n = 129) in patients with neutropenia and without neutropenia, respectively)." (PMID 41155261, 2025).
Arrhythmia (74 papers, 2010 to 2026). Any cardiac rhythm other than the normal sinus rhythm. "In the IR state, enhanced adipocyte inflammation and activation of cytokines such as TNF-α and IL-6 can promote atrial fibrosis and tissue remodeling, increasing susceptibility to arrhythmia." (PMID 41584292, 2025). "IL-6 knockout or neutralization prevented diet-induced inflammation, metabolic defects, and drug- and sterile pericarditis-linked arrhythmias." (PMID 39125976, 2024). "A study titled the Heart and Soul Study also found that IL-6 is closely associated with the incidence of arrhythmias, particularly atrial arrhythmias such as AF." (PMID 39434929, 2024). "Overactivation of IL-6 trans-signaling in guinea pigs prolonged the QT interval, which resulted in greater susceptibility to arrhythmias/SCD with isoproterenol challenge, as also observed with the downstream Janus kinase (JAK) 2 activator." (PMID 39063055, 2024). "IL‐6 via the inflammation pathway has a strong effect in all organs, and other studies have similar findings and have shown an association between increased IL‐6 with an increased risk of arrhythmia in COVID‐19 patients." (PMID 38339786, 2024). "Atrial inflammatory signals, including IL6 secreted by cardiac cells, promote structural and functional remodeling predisposing to arrhythmias." (PMID 39596280, 2024). "The pivotal role of IL-6 and Cx43-signalling identified here highlights these pathways as potential therapeutic targets to reduce the risk of arrhythmia following hiPSC-CMs transplant post-MI." (PMID 37668685, 2023). "Of these cytokines, interleukin (IL)-6 plays a pivotal role in arrhythmia generation as it causes displacement of a desmosomal protein named plakoglobin that is responsible for cell-to-cell adherence and hence it causes cell membrane damage." (PMID 34459992, 2021). "Such additional inflammatory influences are implicated by the pronounced increase in IL-6 in patients with arrhythmias in our cohort." (PMID 33401735, 2021). "Increased IL-6 level has been associated with acquired long QT-syndrome in patients with systemic inflammation, leading to higher risks for arrhythmias such as torsade de pointes." (PMID 32426374, 2020). "What are the other key cellular pro-arrhythmic electrical mechanisms (IKs, INa, ICa,L, IK1, and Ca handling) targeted by the IL-6 trans-signaling pathway, and how might they promote arrhythmia/SCD risk?" (PMID 39125976, 2024). "In addition, IL-6 alters calcium handling and decreases cardiac contractility, which causes diastolic dysfunction and arrhythmia." (PMID 38977536, 2024). "Interestingly, the exercise-induced increase of IL-6 after the marathon in 20 lean male runners was associated with a lower prevalence of arrhythmias during and after the marathon race." (PMID 29089897, 2017). "The use of cytokine inhibitors, such as IL-1 receptor antagonists, TNF-α blockers, and IL-6 inhibitors, has shown potential in other inflammatory diseases, and their application in arrhythmia management is under investigation." (PMID 40901119, 2025). "Cytokines like IL-6, TNF-α, and CRP disrupt cardiac function, increase oxidative stress, and promote fibrosis, heightening arrhythmia risk." (PMID 40281050, 2025). "In the POAF group, the pericardial IL-6 level was 26 times higher compared to the blood value and strengthened the argument that it can be used as a biomarker in the occurrence of arrhythmia." (PMID 40002559, 2025). "As inflammatory cytokines like TNF-α and IL-6 promote the generation of ROS, therapeutic strategies aimed at reducing oxidative stress hold potential in preventing arrhythmias." (PMID 40901119, 2025). "We have recently discovered in a guinea pig heart model that hyper-IL-6 (hIL-6) alone profoundly prolongs the QT interval and directly triggers arrhythmias." (PMID 39125976, 2024). "Left stellectomy in experimental autoimmune myocarditis rats prevented arrhythmias and reduced IL-6 and TNFα levels." (PMID 38256155, 2024).
Arrhythmia (continued). "The inflammatory results obtained in this study are consistent with other research, which has demonstrated a correlative relationship between the systemic inflammatory marker IL-6 and the incidence of arrhythmias." (PMID 39434929, 2024). "Other proinflammatory mediators that link neutrophils to arrhythmia in the context of MI include IL-1β, IL-6, and IL-17A." (PMID 38099844, 2024). "Patients with arrhythmias during hospitalization showed elevated cardiac biomarkers and elevated levels of IL-6." (PMID 33401735, 2021). "Several studies have described the increase in CRP and IL-6 levels in patients with paroxysmal and permanent AF and suggest that the presence of inflammation promotes the development or perpetuates arrhythmia." (PMID 33535417, 2021). "Previous studies demonstrated that arrhythmias are related to proinflammatory cytokines such as interleukin 6 and C-reactive protein by the modulation of ion-channel function and aggravation of the sympathetic system." (PMID 33921213, 2021). "Future IL-6 studies in native atrial and ventricular cardiomyocytes and animal models of lipotoxicity are critical for fundamental insights into the functional consequence of IL-6 modulation of Na current in metabolic disease-related arrhythmias." (PMID 30666212, 2018). "Given that cytokines such as TNF-α, IL-1, and IL-6 contribute significantly to myocardial remodeling, ion channel dysfunction, oxidative stress, and autonomic dysregulation, targeting these pathways offers promising avenues for arrhythmia treatment." (PMID 40901119, 2025). "In contrast, IL-6 protein levels in pericardial fluid collected at the time of arrhythmia exhibited a much greater magnitude of increase in patients with poAF versus sinus rhythm, indicating that postsurgical changes in IL-6 are more pathologically important than preexisting alterations." (PMID 40048254, 2025). "On the other hand, an increased macrophage infiltration has previously been suggested to reflect a defensive mechanism to help remove dysfunctional mitochondria from cardiomyocytes and IL-6 knockout mice exhibited arrhythmia and increased oxidative stress upon LPS injection." (PMID 39821755, 2025). "Thus, another beneficial effect of ExT on CCC was to bring IL-6 levels closer to control group, which probably favored the improvement of arrhythmias as observed in this study." (PMID 40356773, 2025). "Accordingly, this pilot study was aimed at evaluating if some clinical characteristics and interleukin-6 (IL-6), a marker of inflammation, could be useful to describe frailty in older patients with the arrhythmia." (PMID 39639933, 2024). "Using blind-stick and electrocardiogram (ECG) techniques, we tested the hypothesis that heightened IL-6 trans-signaling would exhibit increased ventricular arrhythmia/SCD incidence and underlying arrhythmia substrates." (PMID 39063055, 2024). "We hypothesized that IL-18 may heighten IL-6 effects on ventricular electrophysiology and arrhythmia risks." (PMID 39063055, 2024). "Additionally, the Bz/AMD combination reduced (i) interleukin-6 (IL-6) levels in cardiac tissue, (ii) P-wave duration, and (iii) frequency of arrhythmia in infected animals and (iv) restored gap junction integrity in cardiac tissue." (PMID 35138142, 2022). "IL-6 additionally inhibits cytochrome P450 activity and accordingly can increase the bioavailability of many medications and worsen the drug–drug interactions and incline QTc/TdP arrhythmia." (PMID 34459992, 2021). "Elevated CK, CK-MB, LDH, and IL-6 levels and emerging arrhythmia are associated with the development of severe disease and need for ICU admission, and the mortality is significantly higher in patients with elevated LDH and IL-6 levels." (PMID 32723362, 2020). "Correlation between IL-6, cardiac ion channel expression, and contractile function in arrhythmias." (PMID 30666212, 2018).
Arrhythmia (continued). "Our results showed that clofibrate, as a PPAR-α agonist, succeeded to induce antiarrhythmic effects by delaying the onset and reducing the intensity of ouabain-induced arrhythmias and reduction of ouabain-induced elevation of inflammatory cytokines especially IL-6 in isolated rat atria." (PMID 26977143, 2016). "Interleukin-6, tumor necrosis factor-alpha, and other cytokines released after rituximab use may lead to cardiac arrhythmias, vasoconstriction, platelet activation, and/or rupture of atherosclerotic plaque." (PMID 25023062, 2014). "Patients with AFIB had higher IL-6 levels during AFIB than during sinus rhythm, indicating an acute response during arrhythmia." (PMID 38256155, 2024). "Comparison between inflammatory markers (IL-6, CRP, and procalcitonin) and arrhythmia incidence showed that inflammatory markers were significantly higher in patients with arrhythmia (IL-6: p=0.013, CRP: p=0.025, procalcitonin: p=0.001)." (PMID 39434929, 2024). "In several case-controlled studies, increased levels of inflammatory markers, such as CRP, IL-6, IL-8, and TNF, and elevated neutrophil and lymphocyte ratios have been reported in patients with arrhythmia compared with those in patients with sinus rhythm." (PMID 33796569, 2021). "Serum levels of interleukin-6 in patients with arrhythmia were slightly but not significantly higher as compared to those without arrhythmia." (PMID 36158797, 2022). "There was a significant decrease in postoperative IL-6(P=0.018) and IL-8 (P=0.005) in the ω-3PUFA group, in addition to a reduction in the incidence of arrhythmia, though thelatter was not statistically significant." (PMID 30916121, 2019). "A significant decline in postoperative IL-6 (cytokine) was found in the ω-3 PUFA group, as well as a reduced incidence of arrhythmias, but without significant between-group differences." (PMID 28427403, 2017).